USH2A (usherin)
Description:
Involved in hearing and vision as member of the USH2 complex. In the inner ear, required for the maintenance of the hair bundle ankle formation, which connects growing stereocilia in developing cochlear hair cells. In retina photoreceptors, the USH2 complex is required for the maintenance of periciliary membrane complex that seems to play a role in regulating intracellular protein transport.
Synonyms: RP39; US2; USH2; dJ1111A8.1
Tractability: Antibody: UniProt places it where antibodies can reach, with medium confidence; UniProt predicts a signal peptide or a membrane-spanning region; its Gene Ontology location is reachable by antibodies, with medium confidence. PROTAC: ubiquitination databases record sites on it.
Gene: Protein-coding gene on chromosome 1 (215,622,891 to 216,423,448, reverse strand). Ensembl gene ENSG00000042781.
Subcellular location: Cell projection, stereocilium membrane; Secreted (Isoform 2)
Subcellular location (Human Protein Atlas): Acrosome; Equatorial segment; Mid piece; Principal piece; End piece
Gene Ontology:
Molecular function: collagen binding; myosin binding; protein binding; identical protein binding
Biological process: inner ear receptor cell differentiation; maintenance of animal organ identity; photoreceptor cell maintenance; sensory perception of light stimulus; sensory perception of sound; establishment of protein localization; hair cell differentiation; neuron differentiation; sensory organ development
Cellular component: basement membrane; cytoplasm; stereocilia ankle link; apical plasma membrane; neuronal cell body; periciliary membrane compartment; photoreceptor connecting cilium; photoreceptor inner segment; stereocilia ankle link complex; stereocilium bundle; stereocilium membrane; terminal bouton; USH2 complex; ciliary basal body; extracellular region
Genetic constraint (gnomAD): Loss-of-function variants: 442 observed, 559.49 expected, observed/expected ratio (o/e) 0.79, 90% interval 0.73 to 0.86. The upper end of that interval is the gene's LOEUF score, 0.86, which puts it in group 3 of 6, group 1 being the genes least tolerant of losing a copy. Missense variants: 6,630 observed, 6,655.1 expected, observed/expected ratio (o/e) 1, 90% interval 0.98 to 1.02. Synonymous variants: 2,412 observed, 2,396.2 expected, observed/expected ratio (o/e) 1.01, 90% interval 0.97 to 1.04.
Gene-disease validity (ClinGen):
ClinGen rates the evidence that USH2A causes each of these diseases.
Usher syndrome type 2 (autosomal recessive): Definitive. A syndrome characterized by congenital, bilateral sensorineural hearing loss that is mild to moderate in the low frequencies and severe to profound in the higher frequencies, no abnormalities in the vestibular system, and retinitis pigmentosa.
Homologues: Orthologues: chimpanzee USH2A (99% identical), macaque USH2A (96% identical), guinea pig USH2A (76% identical), rat Ush2a (71% identical), mouse Ush2a (71% identical), tropical clawed frog USH2A (53% identical), zebrafish ush2a (52% identical). Paralogues in human: LAMA5 (10% identical), LAMA3 (9% identical), LAMA2 (9% identical), LAMA1 (9% identical), HSPG2 (9% identical), LAMB1 (7% identical), LAMB2 (6% identical), LAMB4 (6% identical), LAMA4 (6% identical), AGRN (6% identical), LAMC1 (6% identical), LAMC3 (6% identical), and 15 more.
Diseases named in the same sentence as USH2A in open-access papers:
USH2A is named in the same sentence as 121 diseases in open-access papers, as found by Europe PMC text mining. Sharing a sentence is not in itself a finding about the gene and the disease. The quoted sentences say what the papers report.
Usher syndrome (162 papers, 2010 to 2026). A syndromic diseae characterized by the association of sensorineural deafness (usually congenital) with retinitis pigmentosa and progressive vision loss. "Pathogenic variants in the USH2A gene result in Usher syndrome, a group of autosomal recessive rare genetic disorders that affects both hearing and vision." (PMID 40235854, 2025). "Pathogenic variants in the EYS (eyes shut homolog) and USH2A (Usher syndrome type 2A) genes are responsible for a substantial proportion of retinitis pigmentosa (RP) worldwide and are the most prevalent genetic causes of RP in East Asia." (PMID 39932467, 2025). "Exome sequencing allowed the identification of two variants within the USH2A (NM_206933.4) gene, which is linked to Usher syndrome type 2A (MIM: #276901)." (PMID 41007806, 2025). "For example, two patients carried biallelic variants within the ADGRV1 and USH2A genes, both associated with Usher syndrome." (PMID 41007806, 2025). "Mutations in USH2A are responsible for a subtype of Usher syndrome, the most common cause of combined deaf-blindness in humans." (PMID 40564318, 2025). "We compare the Cas13 effectors PspCas13b and Cas13bt3 for the repair of the gene USH2A, a common cause of inherited retinal disease and Usher syndrome." (PMID 39922978, 2025). "Participant #7, who was suspected to have Usher’s syndrome based on hearing loss, tested positive for 2 genetic variants of USH2A, 1 pathologic variant and 1 variant of uncertain significance." (PMID 39328826, 2025). "Biallelic pathogenic variants in USH2A lead to Usher syndrome or non-syndromic retinitis pigmentosa, and shown to have geographical and ethnical distribution in previous studies." (PMID 38879497, 2024). "The most frequently implicated gene in cases of Usher syndrome was USH2A, containing disease-causing biallelic variants for 33.9% of families, followed by MYO7A in 24.2% of all families." (PMID 38189974, 2024). "Ten patients with a genetically confirmed retinitis pigmentosa in Usher syndrome due to biallelic variants in MYO7A or USH2A were enrolled in the study." (PMID 38984112, 2024). "It plays a crucial role in cochlear development and consequently, the perceptiod5z4 bgbvgcn of sound, and therefore USH2A mutations can result in the hearing impairment phenotype of Usher syndrome." (PMID 38891944, 2024). "The second most common gene causing syndromic hearing loss carriers was USH2A (Usher syndrome) (0.97%, 16/1642)." (PMID 38167091, 2024). "Mutations in USH2A are the most commonly observed among all Usher-syndrome-related genes and are also frequently found in autosomal recessive non-syndromic retinitis pigmentosa." (PMID 38474133, 2024). "For USH2A-associated Usher syndrome, the most prevalent disease-causing variant was c.920_923dup p.(His308Glnfs*16), previously reported in multiple European cohorts." (PMID 38189974, 2024). "Mutations in the USH2A gene encoding usherin protein induce autosomal recessive non-syndromic RP and Usher syndrome." (PMID 38012786, 2023). "Given that USH2A mutations are linked to Usher syndrome, a genetic disorder characterized by retinal degeneration, it is plausible that our findings hold relevance to understanding the pathophysiological mechanisms at play in the human context." (PMID 38086867, 2023). "AON-based skipping of a coding region was also previously investigated for USH2A-associated retinitis pigmentosa (RP) and Usher syndrome (USH) variants that result in a premature stop of translation or in damaging amino acid substitutions." (PMID 37587475, 2023). "The focus of the review is Usher Syndrome Type 2A since mutations within USH2A account for over 50% of Usher Syndrome cases and up to 79% of Usher 2 patients." (PMID 37108761, 2023). "The USH2A gene variants were reported to be the most common cause (29%) of Usher syndrome and one of the most common causes (19%–23%) of ARRP." (PMID 36875754, 2023).
Usher syndrome (continued). "Nontruncated variants reportedly have various levels of pathogenicity in USH2A-related Usher syndrome." (PMID 37981655, 2023). "The Usher syndrome is also associatedwith mutations in the USH2A gene encoding the usherin protein,which is involved in sound and light perception as a member of the USH2complex." (PMID 38234607, 2023). "USH2A gene mutations represent the most frequent cause of Usher syndrome and account for 57–79% of USH2 cases." (PMID 35870892, 2022). "Another variant (p.Cys732fs), cosegregating with biallelic USH2A variants in a patient with Usher syndrome, unique to the long isoform, was identified as a Usher syndrome modifier." (PMID 35715776, 2022). "In Usher syndrome patients with biallelic USH2A variants, another heterozygous PDZD7 variant causes earlier-onset and more severe retinal disease." (PMID 35715776, 2022). "Usherin (USH2A) variants are associated with retinitis pigmentosa (RP) or usher syndrome (USH) phenotypes." (PMID 36110214, 2022). "Variants from three known Usher syndrome genes USH2A, USH1G, and USH1C were found from the records retrieved." (PMID 34609590, 2022). "We highlight ABCA4 and USH2A with a CF of ~7% and ~3%, respectively, with the first being responsible of Stargardt disease and the later causing Usher syndrome." (PMID 35955564, 2022). "Our study identified a total of seven pathogenic mutations for Usher syndrome, which are compatible with previously reported pathogenic mutations in the USH2A gene." (PMID 36003347, 2022). "Most of the syndromic diagnoses masquerading as NSHL were related to Usher syndrome (eight patients with causative mutations in the USH2A gene, three in the MYO7A gene, and one in the ADGRV1 gene)." (PMID 36555390, 2022). "This is in keeping with previous reports that show patients with Usher syndrome type 2A develop symptoms at a younger age compared to patients with NS-ARRP associated with USH2A mutations (median age, 15 years vs. 25 years; p < 0.001)." (PMID 36011334, 2022). "The stop-gain variant c.187C>T: p.Arg63* in USH2A is common and has been observed in individuals with Usher Syndrome." (PMID 36140798, 2022). "Since mutations in USH2A are among the most common causes of non-syndromic RP and Usher syndromes, therapies targeting the hotspot mutant regions of USH2A would benefit a large proportion of IRD patients." (PMID 36034145, 2022). "A frequent Usher syndrome-causing USH2A mutation results in incorporation of a psuedoexon and truncation of the USH2A protein." (PMID 33435268, 2021). "The patients of Family 7 and Family 47 with Usher syndrome type 2A presented with retinitis pigmentosa and hearing impairment, harbouring different mutations in the USH2A gene." (PMID 33781268, 2021). "Approximately 2/3 of the patients with Usher syndrome suffer from USH2, of whom 85% have mutations in the USH2A gene." (PMID 34070435, 2021). "In two ARRP subjects carrying biallelic pathogenic variants in USH2A, clinical reassessment disclosed mild hypoacusia and these cases are under specialized evaluation for their possible reclassification to Usher syndrome." (PMID 31736247, 2020). "Mutations in USH2A (MIM #608400) are the most frequent cause of Usher syndrome, accounting for up to 85% of USH2 cases, as well as causing up to 23% of non-syndromic autosomal recessive RP." (PMID 31998945, 2020). "Ataluren is also shown to have a similar effect in Usher syndrome patient-derived cells expressing a nonsense mutation in the USH2A gene." (PMID 32575694, 2020). "An interesting case is also represented by patient RP_38, who presented disease mutations in a gene causative of Usher Syndrome (USH2A), Bardet-Biedl Syndrome (BBS2), retinitisp (AIPL1) and choroideremia (CHM)." (PMID 33374679, 2020). "Nonsense mutations occur in 12% of Usher syndrome patients and have been described in different genes, such as the USH2A gene." (PMID 32575694, 2020).
Usher syndrome (continued). "USH2A is responsible for about 80–90% of Usher syndrome type II and USH2A-causing Usher syndrome is called Usher syndrome type IIa, which is an autosomal recessive disease." (PMID 33105608, 2020). "Our behavioural investigations of the mouse model indicate that heterozygous disruption of Ush2a leads to altered low-frequency hearing thresholds, a phenotype distinct from the high-frequency hearing loss of Usher syndrome (and replicated in null Ush2a mice)." (PMID 32313182, 2020). "USH2A, which is the most common genetic cause of Usher syndrome, was the most frequently mutated gene in our cohort, accounting for over one third of the cases analyzed (9 out of the 25 solved familial cases)." (PMID 31877679, 2019). "Using a multi-omic approach, we identified three novel pathogenic variants in two Usher syndrome genes (USH2A and ADGRV1) in cases initially referred for isolated vision or hearing loss." (PMID 31046701, 2019). "Variant c.11864G>A in USH2A is one of the two most common pathogenic variants found in patients with Usher syndrome type 2A in Europe." (PMID 29293505, 2018). "The aim of this study was to detect USH2A mutations in a Chinese cohort of 75 small RP families and 10 Usher syndrome families." (PMID 29899460, 2018). "Mutations in USH2A cause both isolated Retinitis Pigmentosa (RP) and Usher syndrome (that implies RP and hearing impairment)." (PMID 29912909, 2018). "Mutations in Usherin 2A (USH2A) are not only a frequent cause of Usher syndrome, but also nonsyndromic RP." (PMID 28894305, 2017). "Overall, our data suggest that patients with Usher syndrome due to USH2A mutations have a more attenuated 30 Hz-flicker response compared to their NSRP counterparts." (PMID 28894305, 2017). "Mutations in the USH2A gene are also responsible for a subtype of Usher syndrome which is the most frequent cause of combined deaf-blindness in man." (PMID 28499406, 2017). "This gene is commonly associated with Usher syndrome and non-syndromic RP but, after clinical reassessment, two solved cases harbouring USH2A mutations presented clinical characteristics resembling CRD." (PMID 28157192, 2017). "Four turned out to be atypical Usher syndrome: adult-onset mild neurosensorial hearing loss (RP-1735, RP-1979, RP-0338 and RP-0344 with mutations in USH2A) and one cone-rod dystrophy (CRD) (RP-1543 with mutations in ABCA4)." (PMID 26806561, 2016). "The region on chromosome 1q32.3–41 contains USH2A (haploPS P-value = 0.0391), which encodes usherin, and is responsible for most of the Usher syndrome cases that are characterized by deafness and blindness." (PMID 26879527, 2016). "Our findings expanded the spectrum of known USH2A mutations and reflected the significant implication of USH2A in Usher syndrome." (PMID 26377068, 2015). "Defects in USH2A cause both isolated retinal disease and Usher syndrome (ie, retinal disease and deafness)." (PMID 25649381, 2015). "When allelic heterogeneity was studied and compared with that reported in Usher syndrome, the concept of ‘retinal disease-specific' USH2A alleles (ie, alleles associated with retinal degeneration and no hearing complaint in childhood) became apparent." (PMID 25649381, 2015). "Proband 3 has a missense mutation (p.Leu2886Phe) in the USH2A gene that has been previously associated with Usher Syndrome in a Spanish family." (PMID 25528277, 2014). "Ush2a encodes the protein Usherin, mutations in which can lead to Usher syndrome, a developmental disease affecting both the visual and auditory pathways." (PMID 25374512, 2014). "Usher syndrome is caused by mutations in any of more than ten genes, but the most commonly affected is USH2A, which encodes a protein called usherin." (PMID 23991284, 2013). "Families 5, 6, and 7 appeared to have candidate mutations or variants in MYO7A, CDH23, PCDH15, and USH2A, all of which are associated with Usher syndrome." (PMID 24164807, 2013).
Usher syndrome (continued). "Third, mutations in USH2A were associated with Usher Syndrome type 2A, a syndromic form of deafness characterized by congenital deafness and later development of progressive retinitis pigmentosa (RP)." (PMID 23767834, 2013). "Mutations in the gene for Usher syndrome 2A (USH2A) are causative for non-syndromic retinitis pigmentosa and Usher syndrome, a condition that is the most common cause of combined deaf-blindness." (PMID 23351521, 2012). "At least nine genes have been identified as underlying Usher syndrome; yet most mouse mutants (except whirlin and usherin that cause type II Usher syndrome) bearing one of these mutations develop hearing deficits but not visual dysfunction." (PMID 23351659, 2012). "It is estimated that up to 85% of patients with USH2 and about half of all patients with Usher syndrome have mutations in USH2A." (PMID 23351521, 2012). "Alterations in a number of proteins, including the cell-cell adhesion protein PCDH15 and transmembrane protein USH2A, are thought to directly contribute to the defects associated with Usher syndrome." (PMID 23144817, 2012). "Mutations in USH2A, are also responsible for atypical Usher syndrome and recessive non-syndromic RP." (PMID 22004887, 2011). "In the present study, we have performed a wide mutational screening of the USH2A gene in 88 unrelated Spanish patients diagnosed with Usher syndrome." (PMID 22004887, 2011). "Finally, USH2A has been implicated in Usher syndrome, which is responsible for normal cochlear hair cell development, and we identified a novel variant, c.12607C>T (p.Q4203X), in a homozygous individual." (PMID 39336818, 2024). "Usher syndrome is caused by a USH2A genetic abnormality (OMIM 608400) and will be discussed later." (PMID 39271608, 2024). "The USH2A gene is a representative causative gene of Usher syndrome." (PMID 39271608, 2024). "Targeting specific mutations in genes like USH2A (Usher Syndrome) or CEP290." (PMID 39439625, 2024). "Besides GJB2-related hearing loss, we also identified 3.3% (1 in 31) of women carrying the USH2A gene that caused Usher syndrome, characterized by moderate to severe deafness at birth and progressive retinitis pigmentation." (PMID 38553482, 2024). "The pathogenic variant c.920_923dup p.(His308Glnfs*16) was the most frequently encountered variant in USH2A-associated Usher syndrome (n = 5/5; families/patients), while c.397dup p.(His133Profs*7) was the most frequent variant for MYO7A-associated cases (n = 4/7; families/patients)." (PMID 38189974, 2024). "USH2A, coding for USH2A or Usherin, is one of the most common genes associated with Usher syndrome." (PMID 36830640, 2023). "Mutations in the USH2A gene are the most common cause of Usher syndrome." (PMID 36003347, 2022). "In addition, this group recently investigated morpholino-induced skipping of a mutated exon in ush2a mutant zebrafish (preprint); specifically, they skipped mutant exon 13, which is commonly mutated in Usher syndrome." (PMID 33435268, 2021). "The use of patient-derived retinal organoids, which have already been generated for Usher syndrome caused by USH2A mutations, will further aid in the testing of novel treatments by providing the opportunity to demonstrate therapeutic potential in retinal-specific cells in vitro." (PMID 32995707, 2020). "Usher syndrome is a ciliopathy or disorder caused by a defect in ciliary protein trafficking, and many of the Usher gene protein products, including myosin VIIa, cadherin 23, usherin, and harmonin, are thought to be expressed in retinal ganglion cells." (PMID 33083048, 2020). "Furthermore, the pathogenic change c.9799T > C/p.(Cys3267Arg) in USH2A is one of the most frequent variants in the Spanish population, specifically the third most common cause of Usher syndrome." (PMID 33297549, 2020). "Besides the USH2A gene, Usher syndrome also was caused by ABHD12 (1; 5%), CLRN1 (1; 5%), and MYO7A (8; 40%) genes." (PMID 30374144, 2018).